CORIN (corin, serine peptidase)
Description:
Serine-type endopeptidase involved in atrial natriuretic peptide (NPPA) and brain natriuretic peptide (NPPB) processing. Converts through proteolytic cleavage the non-functional propeptides NPPA and NPPB into their active hormones, ANP and BNP(1-32) respectively, thereby regulating blood pressure in the heart and promoting natriuresis, diuresis and vasodilation. Proteolytic cleavage of pro-NPPA also plays a role in female pregnancy by promoting trophoblast invasion and spiral artery remodeling in uterus. Also acts as a regulator of sodium reabsorption in kidney (By similarity). [Isoform 2]: Has weaker endopeptidase activity compared to isoform 1.
Synonyms: CRN; TMPRSS10; PRSC; ATC2; Lrp4; CMH30; PEE5
Tractability: Antibody: UniProt places it where antibodies can reach, with high confidence; its Gene Ontology location is reachable by antibodies, with high confidence; UniProt predicts a signal peptide or a membrane-spanning region; the Human Protein Atlas places it where antibodies can reach.
Gene: Protein-coding gene on chromosome 4 (47,593,999 to 47,838,132, reverse strand). Ensembl gene ENSG00000145244.
Subcellular location: Cell membrane; Cell membrane (Isoform 2); Secreted (Atrial natriuretic peptide-converting enzyme, 180 kDa soluble fragment); Secreted (Atrial natriuretic peptide-converting enzyme, 160 kDa soluble fragment); Secreted (Atrial natriuretic peptide-converting enzyme, 100 kDa soluble fragment)
Subcellular location (Human Protein Atlas): Plasma membrane; Actin filaments; Nuclear bodies
Pathways (Reactome):
Muscle contraction: Physiological factors
Gene Ontology:
Molecular function: endopeptidase activity; protein binding; serine-type endopeptidase activity
Biological process: female pregnancy; peptide hormone processing; regulation of systemic arterial blood pressure by atrial natriuretic peptide; regulation of blood pressure; regulation of cardiac conduction; regulation of renal sodium excretion; proteolysis; regulation of system process
Cellular component: plasma membrane; cell surface; extracellular region; membrane
Genetic constraint (gnomAD): Loss-of-function variants: 85 observed, 97.65 expected, observed/expected ratio (o/e) 0.87, 90% interval 0.73 to 1.04. The upper end of that interval is the gene's LOEUF score, 1.04, which puts it in group 4 of 6, group 1 being the genes least tolerant of losing a copy. Missense variants: 1,123 observed, 1,215.4 expected, observed/expected ratio (o/e) 0.92, 90% interval 0.88 to 0.97. Synonymous variants: 409 observed, 445.83 expected, observed/expected ratio (o/e) 0.92, 90% interval 0.85 to 1.
Homologues: Orthologues: chimpanzee CORIN (99% identical), macaque CORIN (95% identical), pig CORIN (87% identical), rabbit CORIN (85% identical), dog CORIN (85% identical), mouse Corin (83% identical), rat Corin (82% identical), guinea pig CORIN (80% identical), tropical clawed frog corin (71% identical), zebrafish corin (54% identical).
Diseases named in the same sentence as CORIN in open-access papers:
CORIN is named in the same sentence as 34 diseases in open-access papers, as found by Europe PMC text mining. Sharing a sentence is not in itself a finding about the gene and the disease. The quoted sentences say what the papers report.
Hypertension (9 papers, 2019 to 2026). The presence of chronic increased pressure in the systemic arterial system. "In line with this, the family history of the siblings with CHAF‐LA syndrome reveals multiple family members with early onset hypertension, which is also associated with a CORIN variant carrier status." (PMID 38224201, 2024). "In humans, single nucleotide variations (SNVs) in CORIN, the coding gene of corin protein, were associated with susceptibility to heart failure, cardiac hypertrophy, and hypertension." (PMID 37064175, 2023). "In humans, CORIN gene polymorphisms have been associated with susceptibility to heart failure, cardiac hypertrophy, and hypertension." (PMID 37064175, 2023). "In humans, deleterious CORIN variants are associated with impaired natriuretic peptide processing, hypertension, pre-eclampsia, and heart disease." (PMID 36232551, 2022). "To date, many CORIN variants have been reported in patients with hypertension, atrial fibrillation, coronary artery disease, and heart failure (HF)." (PMID 35625445, 2022). "Another recent study in humans identified an association between CORIN variants and salt sensitivity, longitudinal blood pressure changes, and hypertension incidence." (PMID 35625445, 2022). "A recent longitudinal study in humans also identified CORIN variants associated with dietary salt sensitivity, long-term blood pressure changes, and hypertension susceptibility." (PMID 36232551, 2022). "Variants in the CORIN gene are associated with cardiovascular disease, including hypertension, cardiac hypertrophy, atrial fibrillation, heart failure, and preeclampsia." (PMID 35625445, 2022). "A genotype–phenotype genetic association study demonstrated that CORIN T555I/Q568P allele is common in blacks and is associated with higher blood pressure and an increased risk for prevalent hypertension." (PMID 34409072, 2021). "This is the first study to investigate the relationships among CORIN SNPs and methylations, serum corin levels and risk of hypertension in China." (PMID 31856714, 2019). "We evaluated the association between CORIN gene variants and incident hypertension but fail to detect a significant result." (PMID 31856714, 2019). "MANP has shown favorable antihypertensive, natriuretic and diuretic properties in animal models and in humans, and should be considered in resistant hypertension and AFib patients, focusing on those carrying CORIN loss‐of‐function variants and CHAF‐LA syndrome patients." (PMID 38224201, 2024). "Similarly, variants in the CORIN gene have been reported in individuals with hypertension and heart disease." (PMID 37636304, 2023). "Deleterious CORIN variants are associated with hypertension and heart disease." (PMID 37636304, 2023). "In humans, CORIN variants (I555/P568) are associated with hypertension and cardiac hypertrophy." (PMID 34409072, 2021). "The effects of CORIN gene variants on hypertension risk were indirect and would be very small." (PMID 31856714, 2019). "Studies have confirmed the abnormal involvement of CORIN in hypertension and ventricular hypertrophy." (PMID 34409072, 2021). "CORIN is highly expressed in the heart, is vital for maintaining normal blood pressure, and has even demonstrated cardioprotective effects, with CORIN knockout and low corin protein levels increasing the likelihood of hypertension and heart failure." (PMID 41488731, 2026). "Although data from several studies suggested that CORIN variants may contribute to hypertension and heart disease in this high-risk population, the association between CORIN gene variants and incident hypertension has not yet been reported." (PMID 31856714, 2019). "Two studies reported the correlation between a SNP, rs3749585, which is located in the 3'UTR of CORIN, and hypertension, but the results were not conclusive." (PMID 34409072, 2021).
heart failure (6 papers, 2020 to 2026). Inability of the heart to pump blood at an adequate rate to meet tissue metabolic requirements. "Finally, we analyzed the relationships of the expression of the key genes (HSDL2, BCO2, CORIN, and SNORA80E) with that of transcription factors and regulatory genes in samples from patients with diabetes-associated heart failure." (PMID 38883603, 2024). "HSDL2, BCO2, CORIN, and SNORA80E may regulate cardiomyocyte cuproptosis in patients with diabetes mellitus-associated heart failure through effects on the immune system." (PMID 38883603, 2024).
preeclampsia (4 papers, 2014 to 2024). Preeclampsia is a hypertensive disorder of pregnancy that is characterized by new-onset hypertension with proteinuria presenting after 20 weeks of gestation, and depending on mild or severe forms may initially present with severe headache, visual disturbances, and hyperreflexia. "In conclusion, this is the first report of a highly significant association between these two single nucleotide polymorphisms in CORIN gene and preeclampsia." (PMID 25474356, 2014). "The aim of this study was to search for CORIN gene variations and their association to preeclampsia in Caucasian and African women." (PMID 25474356, 2014). "To date, defective CORIN variants have been found in patients with preeclampsia." (PMID 35625445, 2022). "Additional evolutionary and molecular studies will be required to establish a mechanistic connection between the co-option of CORIN into the endometrium, the evolution of hemochorial placentation, and the origins of preeclampsia in the human lineage." (PMID 34623259, 2021). "Among the human recruited genes enriched in disease ontologies related to preeclampsia is CORIN, a serine protease which promotes uterine spiral artery remodeling and trophoblast invasion." (PMID 34623259, 2021). "CORIN expression is also significantly lower in patients with preeclampsia than in normal pregnancies, suggesting that the co-option of CORIN into human endometrium may predispose humans to preeclampsia." (PMID 34623259, 2021). "To date, there are no data on CORIN gene variations in large series of human patients with preeclampsia." (PMID 25474356, 2014). "The aim of our study was to search for CORIN gene variations and their frequency in Caucasian and Sub-Saharan African pregnant women with and without preeclampsia." (PMID 25474356, 2014).
atherosclerosis (2 papers, 2020 to 2024). A disease characterized by the build-up of fatty material and calcium deposition in the arterial wall resulting in partial or complete occlusion of the arterial lumen. "CORIN is a serine protease mainly expressed in the heart that plays an important role in the development of atherosclerosis, and PDGFA is an growth factor involves in cholesterol-induced atherosclerosis." (PMID 39758846, 2024). "CORIN also likely has roles in fibrosis in cardiomyopathy and atherosclerosis." (PMID 32756554, 2020).
diabetes (2 papers, 2021 to 2024). "As expected, many genes merely changed in the sDM group, such as SULF2, GFAP, ABCG1, GCK, ISM1, and CORIN, have been associated with diabetes." (PMID 34880765, 2021).
leiomyoma (2 papers, 2016 to 2017). A well-circumscribed benign smooth muscle neoplasm characterized by the presence of spindle cells with cigar-shaped nuclei, interlacing fascicles, and a whorled pattern. "Lastly, we confirmed that levels of transcript encoding HES6 (P < 0.05), ZBTB16 (P < 0.02), ITPKA (P < 0.05), and CORIN (P < 0.05) were significantly higher in specimens of luteal phase leiomyomas than proliferative phase specimens." (PMID 28637297, 2017).
Allergy (1 paper, 2025). An allergy is an immune response or reaction to substances that are usually not harmful. "Among sex- and allergy-independent migraine-associated genes, CYP26B1 and CORIN deserve particular attention." (PMID 40350427, 2025). "CORIN and CYP26B1 remained LEGs with largest mean log2 FC, with the latter reaching FDR-significance at both time points in allergy-uncorrected analysis." (PMID 40350427, 2025).
colorectal cancer (1 paper, 2019). A primary or metastatic malignant neoplasm that affects the colon or rectum. "Our model also predicted a high binding affinity between Wnt1 and CORIN‒Fz1, which have been indirectly linked through the negative regulation of Wnt1-induced β-catenin accumulation in colorectal cancer cells by CORIN’s major substrate, ANP." (PMID 31454915, 2019).
dilated cardiomyopathy (1 paper, 2020). Cardiomyopathy which is characterized by dilation and contractile dysfunction of the left and right ventricles. "For example, decreased MYL2 and MYH6 gene expression coincided with increased RYR2, HCN4, CORIN, NPPA, ERBB2, and MYH7 gene expression in hypertrophic and/or dilated cardiomyopathy." (PMID 32804947, 2020).
Fanconi anemia (1 paper, 2020). Fanconi anemia (FA) is a hereditary DNA repair disorder characterized by progressive pancytopenia with bone marrow failure, variable congenital malformations and predisposition to develop hematological or solid tumors. "In particular, relying on functional partners of CORIN and MSH5, several additional pathways were involved, including mismatch repair pathway, meiotic recombination pathway, and Fanconi anemia pathway." (PMID 32724329, 2020).
glaucoma (1 paper, 2022). Increased pressure in the eyeball due to obstruction of the outflow of aqueous humor. "Based on two outstanding PE-associated pathways, including glaucoma and PE, identified by GSEA, ten key genes, including IGFBP1, CORIN, and C3, were revealed." (PMID 35647297, 2022).
ischemic stroke (1 paper, 2023). A stroke disorder caused by obstruction of blood flow to the brain, due to thrombotic (local blood clot formation) or embolic (due to a blood clot or other material traveling from another site) event. "In summary, hypermethylation of the CORIN gene promoter was not only associated with prevalent ischemic stroke but also predicted a lower future risk of incident stroke in Chinese adults." (PMID 37064175, 2023).
Kawasaki disease (1 paper, 2024). A rare inflammatory disease characterized by an acute febrile, systemic, self-limiting, medium-vessel vasculitis primarily affecting children. "Plasma concentrations of ARG1, CCL20, CD163, CORIN, CXCL9, PCSK9 and ADAMTS2 were quantified in MIS-C (n = 22), Kawasaki disease (n = 23), definite bacterial (n = 28) and viral (n = 27) disease and healthy controls (n = 8)." (PMID 38359342, 2024).
migraine (1 paper, 2025). "Furthermore, reduced BNP level, a likely result of downregulated CORIN in our study, has been shown to mimic effects of a key mutation in the familial form of migraine on P2X3 receptors in trigeminal neurons and to facilitate trigeminal sensitization, the primary cause for migraine pain." (PMID 40350427, 2025).
Myocardial fibrosis (1 paper, 2021). "Moreover, CORIN over-expression significantly reduced the development of myocardial fibrosis and prolonged life in mice with DCM." (PMID 34946895, 2021).
psoriasis (1 paper, 2020). An autoimmune condition characterized by red, well-delineated plaques with silvery scales that are usually on the extensor surfaces and scalp. "Comparing gene expression in obese versus non-obese skin showed greater gene expression of S100A7A, encoding a calcium binding protein involved in psoriasis, and CORIN encoding a natriuretic peptide converting enzyme, which is expressed in the dermis and is involved in specifying skin colour." (PMID 32826922, 2020).
schizophrenia (1 paper, 2025). A major psychotic disorder characterized by abnormalities in the perception or expression of reality. "The proportion of neurons annotated as excitatory VGLUT1 and 2 neurons was potentially increased in schizophrenia and those annotated as excitatory CORIN+ neurons were reduced compared to controls." (PMID 39397771, 2025).
skin cutaneous melanoma (1 paper, 2016). "The skin tumor could not be ascribed to skin cutaneous melanoma but was more likely to arise from small cell lung cancer with 65 common mutated genes, such as CORIN and ASPM." (PMID 27442652, 2016).
Stroke (1 paper, 2023). Sudden impairment of blood flow to a part of the brain due to occlusion or rupture of an artery to the brain. "DNA methylation levels of the CORIN gene promoter were lower in stroke patients and predicted a higher risk of incident stroke in Chinese adults." (PMID 37064175, 2023). "Because DNA methylation is a modifiable molecular modification, CORIN promoter methylation could be a candidate therapeutic target for the prevention and management of stroke, although the underlying causality is still unclear." (PMID 37064175, 2023). "Therefore, we aimed to examine the association between CORIN gene promoter methylation and the risk of stroke in two independent samples of Chinese adults." (PMID 37064175, 2023). "We further examined whether CORIN promoter methylation assayed in the discovery sample predicted the future risk of stroke in a prospective cohort study – the Gusu cohort as an independent replication sample." (PMID 37064175, 2023). "Here, we examined whether the CORIN promoter’s methylation, an epigenetic DNA modification, was associated with the risk of stroke in two independent samples." (PMID 37064175, 2023). "DNA methylation level of the CORIN promoter, the CpG located at Chr4:47840038 in particular, could be a predictor of incident stroke." (PMID 37064175, 2023). "Our results suggest that CORIN promoter methylation may play a potential role in the development of stroke through mechanisms beyond metabolic factors." (PMID 37064175, 2023). "Because DNA methylation is modifiable, CORIN promoter methylation may serve as a potential predictor or even probably a therapeutic target for stroke." (PMID 37064175, 2023). "As suggested above, we hypothesized that DNA methylation of the CORIN gene may also play a considerable role in stroke development, but lacking epidemiological evidence." (PMID 37064175, 2023).
heart disease (4 papers, 2019 to 2023). "Among them, some have been already reported to be involved in cardiac diseases, such as CORIN and EGLN3." (PMID 31902369, 2020).
cardiovascular disease (2 papers, 2020 to 2022). "Further studies should help us to understand the functional significance of those CORIN variants in specific cardiovascular diseases." (PMID 35625445, 2022). "CORIN is also proposed to be a possbile biomarker for cardiovascular disease complications in T2DM patients." (PMID 32756554, 2020).
CORIN also shares sentences with these, for which no sentence is quoted: cardiac hypertrophy (4 papers); atrial fibrillation (2); infection (2); atopic eczema (1); cardiomyopathy (1); COVID-19 (1); metabolic disease (1); Obesity (1); prostate (1); skin tumor (1); small cell lung carcinoma (1); tumor (1); Ventricular hypertrophy (1).